IDH1 (isocitrate dehydrogenase (NADP(+)) 1)
Diseases named in the same sentence as IDH1 in open-access papers (continued):
Sharing a sentence is not in itself a finding about the gene and the disease.
tumor (continued). "Sequencing of IDH1 and IDH2 was negative for mutation in either tumor sample (data not shown)." (PMID 23047041, 2012). "Therefore, cells within IDH1-positive tumours that are not stained by mIDH1R132 are considered to be non-tumour cells." (PMID 21559010, 2011). "However, precise tumour grading is crucial for improved patient surveillance and treatment, which was emphasised by results from the recently published INDIGO trial showing strong clinical efficacy of the IDH1/2 inhibitor vorasidenib in grade 2 IDH-mutant glioma." (PMID 39382765, 2024). "Furthermore, mutations in the IDH1 gene, as well as depletion of histone chaperone ASF1, have been implicated in the activation of the ALT phenotype, indicating that ALT activation in tumor cells is not solely dependent on ATRX/H3-3A mutations." (PMID 37370681, 2023). "Additionally, in this setting, we would expect enhanced DNA damage, particularly in conjunction with RT and TMZ chemotherapy, which may explain why our patient with a mutant IDH1 GBM responded so favorably to this therapy, especially if DNA repair machinery in the IDH-mutant tumor is impaired." (PMID 37218937, 2023). "In addition, the tumor cells may be positive for nuclear NeuN but negative for cytoplasmic IDH1- R132H, epithelial membrane antigen (EMA), cytokeratin (CK), and nuclear Olig-2." (PMID 33964714, 2021). "Furthermore, by integrating with several factors from multivariate analysis, IDH1 expression in tumors could enhance the prognostic accuracy of these factors, including SSIGN outcome algorithm, TNM stage, N stage, Fuhrman grade and tumor sizes." (PMID 30153799, 2018). "However, IDH1/2 mutations in AML and other tumors are heterozygous and occur in the active catalytic site, suggesting oncogenic gain of new function rather than loss of tumor suppression." (PMID 29882807, 2018). "In addition, DIM-C-pPhOH (30 mg/kg/d) also decreased expression of TXNDC5 and IDH-1 and induced CHOP expression in tumors from athymic nude mouse xenografts, demonstrating that C-DIM/NR4A1 antagonists-dependent inhibition of RCC cell and tumor growth is due, in part, to induction of stress." (PMID 26035713, 2015). "The tumor cells were immunohistochemically positive for GFAP, ATRX, and H3 K27me3, but negative for synaptophysin, IDH1 R132H, and H3 K27M." (PMID 39432011, 2025). "This is important because grade 4 GBM tumors all express functional IDH-1, and remaining GBM tumor cells can therefore not be inhibited by the Shankar approach." (PMID 36901897, 2023). "In tumours, rather than reactivating IDH2 and IDH3, cancer cells remain dependent on this highly active cytoplasmic IDH1." (PMID 37086156, 2023). "The tumor showed a complete response, and the patient did not develop tumor recurrence 9.8 months after the treatment for GBM with IDH1/2 wild-type." (PMID 35505351, 2022). "Alterations in IDH1, FGF19, RB1, and BAP1 appeared in patients with tumor size reduction, but not in those with non-responding tumors." (PMID 35311147, 2022). "Continuous daily treatment with AG-5198 of an IDH1-mut recurrent GBM (MGG152) xenograft model in vivo did not affect mice survival, tumor size, and expression of the proliferative marker Ki-67 compared to controls." (PMID 35267433, 2022). "Genetic analysis of primary tumour revealed KRAS Q61K, wild-type IDH1/2, H3F3A, HIST1H3B and TERT promoter, and no MGMT promoter hypermethylation." (PMID 34525976, 2021). "To estimate the prognostic performance of combined tumor-SVZ distance and IDH1 status in patients without SVZ involvement, we made an additional comparison." (PMID 34490090, 2021).
tumor (continued). "However, in patients with an IDH1R132H tumor, TERTp status did not significantly associate with survival, and multivariate analysis unveiled that TERTp status was not an independent prognostic factor when adjusting for age, WHO grade, and IDH1 status (HR 1.06; 95% CI 0.50–2.24; p = 0.87)." (PMID 31960234, 2020). "In TMZ-receiving patients with GBM harboring wild-type IDH1 and non-G-CIMP, the combined expression of H2AFJ with PMT, TNFα-NF-κB, or IL6-STAT3 geneset exhibited an inverse correlation with time to new tumor event after the treatment." (PMID 31906036, 2019). "The tumor was negative for glial fibrillary acidic protein (GFAP) and isocitrate dehydrogenase (NADP(+)) 1 (IDH1) R132H." (PMID 31480400, 2019). "The tumor cells were labelled by antibodies against GFAP and Olig2 but not by an antibody against isocitrate dehydrogenase 1 (IDH1)-R132H." (PMID 30305059, 2018). "The tumor included a heterogeneous population of GFAP and synaptophysin immunopositive cells and did not stain for either NeuN or IDH1 R132H." (PMID 29872694, 2017). "The tumor was positive for OLIG2 and GFAP and negative for BRAF V600E and IDH1 R132H mutant protein immunostains." (PMID 29141672, 2017). "The tumor demonstrated extensive immunostaining with GFAP and OLIG2 (not shown), and was negative for BRAF V600E and for IDH1 R132H mutant protein." (PMID 29141672, 2017). "Additional immunostains revealed that the tumor cells had intact/retained expression of ATRX protein and were negative for IDH1-R132H mutant protein." (PMID 28699883, 2017). "The tumor was strongly immuno-reactive for GFAP, SMARCB/INI-1 was preserved, and the tumor was negative for chromogranin, synaptophysin, Cam 5.2, EMA, desmin, myogenin, neurofilament and mutant-specific IDH1 (R132H)." (PMID 27582545, 2016). "We isolated proteins from one non-ODG tumour with a 1p deletion, two ODG tumors with 1p19q co-deletions, and cultured ODG cells BT054 (IDH1+/R132H/CIC+/−) and BT088 (IDH1+/+/CICR1515H/−), both containing 1p19q co-deletions." (PMID 25277207, 2014). "This concept is further supported by the inability of IDH1wt overexpression to alter the anti-tumor phenotypes of the JJ012 and HT1080 IDH1 KO cells, as well as by the lack of any significant effects of IDH1 knockout on the properties of non-transformed C28 chondrocytes." (PMID 31935911, 2020). "Second, nonattendance of the tumor-related variables, such as MGMT methylation status and isocitrate dehydrogenase-1 (IDH-1) and IDH-2, and local/systemic reactive proinflammatory cytokine/chemokine levels disallowed us to perform SII group-based analysis according to these biomarkers." (PMID 32565725, 2020). "The tumor cells immunolabeled with GFAP and IDH1, and were negative for EGFR." (PMID 24252196, 2013). "Also, as with IDH1 staining, no cells lining the vessels showed increased EGFR copy number using CISH, supporting the concept that the endothelial lining was not derived from the surrounding tumor." (PMID 22298889, 2012).
cancer (738 papers, 2010 to 2026). A tumor composed of atypical neoplastic, often pleomorphic cells that invade other tissues. "Mutations in IDH1/2 are strongly associated with certain types of cancer (e.g., glioma, leukemia, etc.)." (PMID 40696413, 2025). "The abnormal accumulation of the metabolite D-2-HG in cancers is mainly due to IDH1/IDH2 mutations, which leads to the over-production of D-2-HG." (PMID 41236698, 2025). "The most important cancer-linked mutations of IDH1 occur at arginine-132 which interacts with one of the isocitrate carboxylates." (PMID 40025220, 2025). "The most prevalent IDH1 mutation found in human cancers is R132H, and this residue is strictly conserved." (PMID 40943163, 2025). "In CCA, its efficacy was demonstrated in a Phase III placebo-controlled double-blind trial in patients with IDH1 mutation-positive cancer and a prior treatment history." (PMID 41008893, 2025). "Research on solid tumours, a pan-cancer analysis, has demonstrated that IDH1 mutations occur more frequently and affect a broader range of cancer types compared to IDH2." (PMID 40182999, 2025). "Regarding our case reviews, a series of 4 patients with diverse cancer types, all exhibiting mutations in the IDH1 gene are presented." (PMID 40182999, 2025). "NAD depletion via concomitant NAMPT inhibition has been identified as a metabolic susceptibility of IDH1 mutant cancers and results in cytotoxicity triggered by autophagy." (PMID 40949165, 2025). "Several pioneering studies demonstrate that cancer-associated IDH1 mutations predispose sensitivity to genotoxic stress." (PMID 39920158, 2025). "Cancer cells with IDH1 or IDH2 mutations cause accumulation of 2-HG, which supports the cancer cells by maintaining a stem-like phenotype, while suppressing T-cell- and macrophage-mediated immune activity." (PMID 41235226, 2025). "The work reported here provides evidence that loss of end protection factors in IDH1-mutant cancers leads to PARPi resistance both in vitro and in vivo." (PMID 41357766, 2025). "Overall, these findings highlight the critical role of the IDH1-R132H mutation in cisplatin-induced renal injury, providing important insights for developing personalized treatment strategies for cancer patients." (PMID 39306640, 2025). "The missense and heterozygous cancer-associated mutations typically occur at Arginine 132 in IDH1 and Arginine 172 in IDH2, impairing the ability of mutant IDH to bind with isocitrate." (PMID 40949165, 2025). "IDH1 mutations are among the most studied metabolic alterations in cancers, particularly in gliomas, acute myeloid leukaemia, cholangiocarcinoma, and chondrosarcoma." (PMID 41154605, 2025). "In light of the successful genetic analysis of oncogenic point mutations in the KRAS, PIK3CA, and IDH1 genes of human cancer cell lines using RGEN-RFLP, it can be inferred that WD diagnosis should be possible by using this method." (PMID 39056796, 2024). "In recent years, the development of inhibitors targeting IDH1 mutations has become a research hotspot in cancer therapy." (PMID 39512821, 2024). "While most studies focused on the role of IDH1/2 mutation in cancer, several studies have also revealed the oncogenic role of wild-type IDH1/2 in different cancer types in recent years." (PMID 38167476, 2024). "For example, AG-120 (ivosidenib), an inhibitor of the IDH1 mutant enzyme, has an acceptable safety profile and clinical activity, according to preliminary data from a Phase I clinical trial recruiting cancer patients with the IDH1 mutation." (PMID 39484162, 2024). "As the most frequently mutated metabolic gene in human cancers, IDH1/2 interferes with cell metabolism and epigenetic regulation, thereby promoting tumorigenesis." (PMID 39113352, 2024).
cancer (continued). "IDH1/2 mutations that are associated with cancer tend to localize to the arginine (R) residue that is crucial for the recognition of isocitrate (R132 for IDH1, R140 or R172 for IDH2), with a vast majority of IDH1 R132H events." (PMID 38339779, 2024). "Whereas our results have focused on how the neomorphic idh-1 mutation affects the developing embryo, proliferating cancer cells also have been shown to have increased demand for 1C units, for instance, to synthesize nucleosides." (PMID 39009411, 2024). "Recently, several cancers have been discovered to be associated with gain‐of‐function mutations of isocitrate dehydrogenase 1/2 (IDH1/2) enzyme." (PMID 39113352, 2024). "Isocitrate dehydrogenase 1 and 2 (IDH1 and 2), when mutated, can switch cancer cells from glycolysis to OXPHOS." (PMID 38897995, 2024). "Inhibitors targeting IDH1/2 have been effective in reducing this oncometabolite and promoting differentiation and death in cancer cells with these mutations." (PMID 39199633, 2024). "Metabolically, IDH1 converts isocitrate to α-ketoglutarate, however, mutations of IDH1/2 are frequent in cancer, and lead to conversion of α-ketoglutarate to 2-hydroxyglutarate (2-HG)." (PMID 39282472, 2024). "IDH1/2 is the most frequently mutated metabolic gene in human cancers and interferes with cell metabolism and epigenetic regulation, thereby promoting tumorigenesis." (PMID 39113352, 2024). "Here the authors show mutants of isocitrate dehydrogenase 1 (IDH1), an enzyme implicated in various cancers, have distinct catalytic and structural features that drive their ability to generate an oncometabolite." (PMID 38710674, 2024). "Mutations to IDH1 are thought to be tumorigenic and the R132H single nucleotide variant is established as an important cancer biomarker." (PMID 37733671, 2023). "Cancer-associated mutations in IDH1 and -2 are typically heterozygous and result in substitution of arginine residues within the enzymes’ active site (most commonly R132 of IDH1, or R140 or R172 of IDH2)." (PMID 37526143, 2023). "Here, the “Electrochemical Leaf” is used to extract detailed kinetic and mechanistic information on the inhibitory action of a high‐profile cancer drug that inhibits a common cancer‐associated variant of isocitrate dehydrogenase 1 (IDH1)." (PMID 37607127, 2023). "It has previously been reported that mitochondrial function is essential for cancer cell viability and that mutations in SDHA, FH, and IDH1 can change mitochondrial metabolism and allow cancer cells to adapt to changing environments." (PMID 37190292, 2023). "Ivosidenib is an anticancer drug that works in malignancies with a sensitive IDH1 mutation, which shows elevated levels of the cancer cell oncometabolite D-2-hydroxyglutarate (D-2HG)." (PMID 37631077, 2023). "We obtained the IDH1 mutation information from patients, and nineteen out of 149 cancer patients were confirmed to have an IDH1 mutation by PCR sequencing." (PMID 37741882, 2023). "IDH1/2 mutations in cancer cases are mostly missense variants, causing a single amino acid substitution of arginine residues at codon 132 in the IDH1 gene or codons 140/172 in the IDH2 gene." (PMID 37546420, 2023). "Given tissue-specific enhancer and CTCF chromatin landscapes as well as cancer dependency genes, the epigenetic consequences of IDH1 mutation in CAC and its interplay with inflammation will be an exciting area of future study." (PMID 37884500, 2023). "Somatic mutations in IDH1 and -2 genes in cancer were first reported in the late 2000's and over the past 15 years enormous strides have been made in our understanding of their contribution to oncogenesis." (PMID 37526143, 2023). "Future studies are needed to further investigate the potential of ivosidenib for individualized anti-cachexia effect in cancer patients with an IDH1 mutation." (PMID 37741882, 2023).
cancer (continued). "Variants of isocitrate dehydrogenase (IDH) 1 and 2 (IDH1/2) alter metabolism in cancer cells by catalyzing the NADPH-dependent reduction of 2-oxoglutarate (2OG) to (2R)-hydroxyglutarate." (PMID 36621625, 2023). "The survival analyses revealed that the high expression of IDH1 was significantly associated with a poor prognosis in patients with four cancers." (PMID 37958642, 2023). "IDH is one of the most studied genes in glioma development, and cancers with IDH1 or IDH2 mutations produce 10–100 times more 2-HG than those with the IDH1 or IDH2 wildtype." (PMID 36819921, 2023). "As demonstrated by studies on IDH1 variant inhibition by the pioneering cancer drug, Ivosidenib, the results reveal how the e‐Leaf efficiently provides new and detailed mechanistic insight." (PMID 37607127, 2023). "Considering the widespread abundance of 2-oxoacid and alcohol couples in cells, it seems likely that cancer-associated IDH1/2 variants affect metabolism in ways other than catalyzing the reduction of 2OG to 2HG." (PMID 36621625, 2023). "IDH1 mutation mediated D2HG accumulation contributes to the progression of cancer cachexia and muscle atrophy." (PMID 37741882, 2023). "In general, the variations in the Kmapp-values of the three cancer-associated IDH1/2 variants for the investigated 2OG derivatives are larger than the variations in the kcatapp-values." (PMID 36621625, 2023). "We report binding and inhibition studieson 13 IDH1/2 variant inhibitors, including clinical candidates anddrugs, with wild-type (wt) IDH1 and its cancer-associated variant,IDH1 R132H." (PMID 36952395, 2023). "The average IDH1 alteration frequency of IDH1 was 5% across all cancer, and the most common alteration type was mutation." (PMID 37741882, 2023). "Together, these factors underpin the different prevalence of specific IDH1 and -2 variants in different cancer types, the pattern of co-occurring mutations, response to therapy and prognosis." (PMID 37526143, 2023). "First, IDH1/2 mutations are always monoallelic, suggesting the wildtype activities of IDH1/2 are essential to the survival of cancer cells." (PMID 37546420, 2023). "Here, we used synthetic C3- and C4-alkylated 2OG derivatives to investigate the substrate selectivities of the most common cancer-associated IDH1 variant (R132H IDH1), of two cancer-associated IDH2 variants (R172K IDH2, R140Q IDH2), and of WT IDH1/2." (PMID 36621625, 2023). "The results reveal that of all the 43 small molecules investigated for inhibition, only N-oxalylglycine (NOG) efficiently inhibited all three tested cancer-associated IDH1/2 variants in the presence of equimolar amounts of 2OG." (PMID 36621625, 2023). "In the case of IDH1, the focus of this study, the most common substitutions occur at arginine-132, with the most common cancer-associated substitutes being histidine (R132H) and cysteine (R132C)." (PMID 36574703, 2023). "Differential gene expression was analyzed in public AML RNA-Seq and microarray data in order to identify deregulated cancer-associated genes in patients with IDH1 mutation." (PMID 36411356, 2023). "With respect to IDH1, the most accepted variation is R132H, which contributes ≥89% of mutation and plays a paramount role in the mutation to pledge the cancer progression extensively." (PMID 36903561, 2023). "Overall we confirm that mutations in known cancer drivers accurately reproduce expected associations with both individual metabolites such as IDH1 mutations and 2‐hydroxyglutarate, and pathways such as KEAP1 mutations and glutathione metabolism." (PMID 36321551, 2022). "Our identification of this genetic interaction between complex I gene variants and IDH1 mutation has highlighted the potential for similar exclusivities and unique metabolic vulnerabilities in other cancer settings." (PMID 35551192, 2022).